RN7SKP288 (RN7SK pseudogene 288)
Gene: Miscellaneous RNA gene on chromosome 10 (110,756,456 to 110,756,723, forward strand). Ensembl gene ENSG00000252036.
Homologues: Orthologues: chimpanzee 7SK (99% identical). Paralogues in human: RN7SKP255 (60% identical), RN7SKP281 (58% identical), RN7SKP50 (57% identical), RN7SKP171 (57% identical), RN7SKP153 (57% identical), RN7SKP291 (57% identical), RN7SKP37 (57% identical), RN7SKP115 (56% identical), RN7SKP137 (56% identical), RN7SKP163 (56% identical), RN7SKP212 (56% identical), RN7SKP226 (56% identical), and 283 more.